FAM246C (family with sequence similarity 246 member C (gene/pseudogene))
Gene: Protein-coding gene on chromosome 22 (19,029,524 to 19,031,242, forward strand). Ensembl gene ENSG00000286025.
Homologues: Orthologues: mouse Fam246a (34% identical), rat LOC120095536 (32% identical). Paralogues in human: FAM246A (43% identical), FAM246B (42% identical).